ZKSCAN1 (zinc finger with KRAB and SCAN domains 1)
Description:
May be involved in transcriptional regulation.
Synonyms: KOX18; ZNF139; ZNF36; PHZ-37; ZSCAN33
Tractability: PROTAC: UniProt records ubiquitination sites on it; ubiquitination databases record sites on it; its protein half-life has been measured.
Gene: Protein-coding gene on chromosome 7 (100,015,570 to 100,041,689, forward strand). Ensembl gene ENSG00000106261.
Subcellular location: Nucleus
Subcellular location (Human Protein Atlas): Nuclear bodies; Nucleoplasm; Mitochondria
Pathways (Reactome):
Gene expression (Transcription): Generic Transcription Pathway
Gene Ontology:
Molecular function: protein binding; DNA-binding transcription factor activity, RNA polymerase II-specific; RNA polymerase II cis-regulatory region sequence-specific DNA binding; identical protein binding; sequence-specific double-stranded DNA binding
Biological process: regulation of transcription by RNA polymerase II; regulation of DNA-templated transcription
Cellular component: nucleus
Genetic constraint (gnomAD): Loss-of-function variants: 14 observed, 53.04 expected, observed/expected ratio (o/e) 0.26, 90% interval 0.17 to 0.41. The upper end of that interval is the gene's LOEUF score, 0.41, which puts it in group 1 of 6, group 1 being the genes least tolerant of losing a copy. Missense variants: 531 observed, 745.8 expected, observed/expected ratio (o/e) 0.71, 90% interval 0.66 to 0.76. Synonymous variants: 263 observed, 275.82 expected, observed/expected ratio (o/e) 0.95, 90% interval 0.86 to 1.06.
Homologues: Orthologues: chimpanzee ZKSCAN1 (99% identical), macaque ZKSCAN1 (97% identical), rabbit ZKSCAN1 (93% identical), guinea pig ZKSCAN1 (92% identical), pig ZKSCAN1 (91% identical), mouse Zkscan1 (90% identical), rat Zkscan1 (90% identical). Paralogues in human: ZKSCAN8 (44% identical), ZKSCAN3 (41% identical), ZNF397 (40% identical), ZSCAN30 (40% identical), ZKSCAN4 (40% identical), ZSCAN12 (37% identical), ZSCAN21 (36% identical), ZNF165 (36% identical), ZSCAN26 (35% identical), ZNF263 (34% identical), ZSCAN31 (34% identical), ZSCAN22 (34% identical), and 18 more.
Diseases named in the same sentence as ZKSCAN1 in open-access papers:
ZKSCAN1 is named in the same sentence as 28 diseases in open-access papers, as found by Europe PMC text mining. Sharing a sentence is not in itself a finding about the gene and the disease. The quoted sentences say what the papers report.
bladder cancer (11 papers, 2019 to 2024). "Circular ZKSCAN1, for instance, was described as a tumor suppressor that significantly influenced the proliferative, migratory, and invading capacities of bladder cancer cells." (PMID 37612868, 2024). "Previously, circular RNA circ-ZKSCAN1 was reported to inhibit bladder cancer progression by adsorbing miRNA." (PMID 33656636, 2022). "For instance, circ-ZKSCAN1 inhibits bladder cancer progression through miR-1178-3p/p21 axis and acts as a prognostic factor of recurrence." (PMID 34922539, 2021). "For instance, Circular RNA circ-ZKSCAN1 inhibits bladder cancer progression through miR-1178-3p/p21 axis and acts as a prognostic factor of recurrence." (PMID 34922539, 2021). "Circ-ZKSCAN1 suppresses the progression of bladder cancer through modifying p21 expression via directly sponging miR-1178-3p, which is considered as a potential prognostic signature of recurrence." (PMID 34060415, 2021). "Mechanistically, we demonstrated that circ-ZKSCAN1 upregulated p21 expression by sponging miR-1178-3p, which suppressed the aggressive biological behaviors in bladder cancer." (PMID 31481066, 2019). "Tumorigenesis in nude mice was assessed to determine the effect of circ-ZKSCAN1 in bladder cancer." (PMID 31481066, 2019).
hepatocellular carcinoma (11 papers, 2017 to 2025). A malignant tumor that arises from hepatocytes. "CircRNA ZKSCAN1 interacts with FMRP to prevent the binding of FMRP with CCAR1 complex in hepatocellular carcinoma." (PMID 36800233, 2023). "For example, ZKSCAN1 gene and its related circular RNA (circZKSCAN1) both inhibit hepatocellular carcinoma cell growth, migration, and invasion." (PMID 32185826, 2020). "Yang found that circ-ZKSCAN1 was downregulated in hepatocellular carcinoma and acted as a tumor suppressor." (PMID 31481066, 2019). "It is reported one circRNA, cirZKSCAN1, varied in hepatocellular carcinoma patients with different tumor numbers, cirrhosis, vascular invasion, or the tumor grade, and furthermore, ZKSCAN1 mRNA and circZKSCAN1 cooperated closely with one another." (PMID 28282919, 2017). "In this study, we demonstrated that ZKSCAN1, a zinc finger family gene, is expressed in both linear and circular (circZKSCAN1) forms of RNA in human hepatocellular carcinoma (HCC) tissues and cell lines." (PMID 28211215, 2017). "In the present study, the role of ZKSCAN1 gene and its relative circRNA (circZKSCAN1) in the regulation of hepatocellular carcinoma cell growth, migration, and invasion and the potential mechanism were investigated." (PMID 28211215, 2017). "Notably, the circRNA, hsa_circ_0001727, originated from ZKSCAN1 was reported to inhibit hepatocellular carcinoma cell growth, migration, and invasion through several cancer-related signaling pathways." (PMID 34094907, 2021). "Furthermore, circRNA ZKSCAN1 is capable of suppressing the growth and metastasis of hepatocellular carcinoma cells." (PMID 32706154, 2020).
gastric cancer (9 papers, 2016 to 2025). A primary or metastatic malignant neoplasm involving the stomach. "As a member of the zinc finger protein family, ZKSCAN1 protein has been reported to be located in the nucleus of gastric cancer tissues and to play regulatory roles affecting a variety of genes at the transcriptional level." (PMID 28211215, 2017). "ZKSCAN1 had been reported to be up‐regulated in gastric cancer." (PMID 28211215, 2017). "ZKSCAN1 (or ZNF139) has been reported to have increased expression in gastric cancer cells." (PMID 27923066, 2016). "ZKSCAN1 (also known as KOX18, ZNF139), a node with three connections in the same module with BRIP1, also has been reported to play regulatory roles in migration and invasion of human gastric cancer cells." (PMID 30240439, 2018). "ZKSCAN1 is significantly involved in lymph node metastasis and vascular invasion in gastric cancer, while there are no relevant reports on TRIM63." (PMID 40490947, 2025).
liver fibrosis (2 papers, 2024 to 2025). "Whether rs2897075 is associated with levels of ZKSCAN1 circRNA is unknown, though both ZKSCAN1 and circZKSCAN1 have been implicated in liver fibrosis." (PMID 39876559, 2025).
pancreatic cancer (2 papers, 2022). "A chromatin accessibility signature and associated transcriptional factors (ZKSCAN1 and HNF1β) are significantly correlated with pancreatic cancer prognosis." (PMID 36546899, 2022).
lymph node metastasis (1 paper, 2022). "The chi-square test demonstrated an association between low circ-ZKSCAN1 levels and advanced clinicopathological features including high histological grade, pathological T stage, and lymph node metastasis in BCa patients." (PMID 35296022, 2022).
medulloblastoma (1 paper, 2021). A malignant, invasive embryonal neoplasm arising from the cerebellum. "The seven circRNAs, FKBP8, SMARCA5, GLIS1, BACH1, ZKSCAN1, CDYL, and OGDH, with a reduced expression in medulloblastoma versus cerebellum, while their corresponding linear mRNAs do not follow this change of expression pattern, were selected for further analysis." (PMID 34680287, 2021).
prediabetes (1 paper, 2020). "In conclusion, our present results show that mild prediabetes induces miRNA expression changes leading to altered gene expression of Jazf1, Zkscan1, and Rap2c, which may contribute to the diastolic dysfunction and may serve as potential drug targets." (PMID 32244869, 2020).
tumor (21 papers, 2017 to 2025). "Circ-ZKSCAN1 levels were associated with survival, tumor grade, pathological T stage and tumor recurrence." (PMID 31481066, 2019). "Tumor number, cirrhosis, vascular invasion, microvascular infiltration (MVI), and tumor grade are the major factors associated with the circ-ZKSCAN1 expression level." (PMID 30064463, 2018). "Of all the clinical parameters, a low expression level of ZKSCAN1 was only associated with a tumor size less than 5 cm (P = 0.032)." (PMID 28211215, 2017). "Additionally, we found that lower expression of circ-ZKSCAN1 was significantly associated with poorer disease free survival, higher recurrence and a positive tumor metastasis status, suggesting its tumor-suppressive effect on BCa." (PMID 31481066, 2019). "Circ-ZKSCAN1 expression was higher in healthy tissue, suggesting that its downregulation in tumor tissue contributes to carcinogenic establishment, as well as a potential role for this molecule as a tumor suppressor." (PMID 37373059, 2023). "Other studies have also revealed that miR-330, originating from SINE sequences, has a direct connection with tumor-suppressive circ_0078767 and oncogenic circ-ZKSCAN1 in NSCLC." (PMID 36769372, 2023). "The expression quantities of circ-ZKSCAN1 have been revealed to be decreased in BC tissues, and low levels of circ-ZKSCAN1 are positively related with tumor size, grade, recurrence, and lymph node metastasis." (PMID 34572845, 2021). "Circ ZKSCAN1 was markedly down-regulated in BC tissues and cells and with survival, tumor grade, pathological stage, and tumor recurrence." (PMID 33489913, 2020). "Circ-ZKSCAN1 is downregulated in BCa and correlates with tumor metastasis status, recurrence, pathological T stage and histological grade." (PMID 31481066, 2019). "Compare to the NC group,the expression of p21 was obviously increased in tumor tissues of circ-ZKSCAN1-overexpressed group." (PMID 31481066, 2019). "For instance, although both circ-ZKSCAN1 and ZKSCAN1 were downregulated in hepatocellular carcinoma cancer, they influenced the proliferation and migration of tumor cells through different biological pathways." (PMID 29844435, 2018). "ZKSCAN1 is a kind of zinc family gene, which is upregulated and related to the proliferation of tumor cells in several cancers." (PMID 30191143, 2018). "(2009) found that increased ZKSCAN1 expression in adenocarcinoma at the esophagogastric junction was related to the proliferation of tumor cells." (PMID 28211215, 2017). "Similarly, upregulation of circ-ZKSCAN1 was closely related to poor prognosis, malignant characteristics, tumor stage, and tumor size in patients with lung cancer." (PMID 34400888, 2021). "Remarkably, miR-1178-3p mimics could partially alleviate the tumor-suppressing effect of circ-ZKSCAN1." (PMID 31481066, 2019). "Taken together, these findings indicate that circ-ZKSCAN1 is a tumor suppressor in BCa." (PMID 31481066, 2019). "The downregulation of ZKSCAN1 mRNA was correlated with tumor size while circZKSCAN1 levels affected tumor number, cirrhosis, vascular invasion or microscopic vascular invasion and tumor grade." (PMID 30191143, 2018). "The feedback loop among oncogenic circRNAs, circ-ZKSCAN1, miR-330-5p, and FAM83A is closely related to malignant characteristics, such as poor prognosis, larger tumor size, and advanced clinical stage." (PMID 36769372, 2023). "Specifically, it is reported that circ-ZKSCAN1 can inhibit the growth of NSCLC cells, and its high expression is closely related to the malignant characteristics of the tumor and the poor prognosis of the patients." (PMID 35917658, 2022). "After subcutaneous injection of pcDNA3.1(+) ZKSCAN1 MCS Exon Vector and pcDNA3.1(+) ZKSCAN1 MCS Exon Vector with hsa_circ_0000190 gene using nanoparticle transfection technology, the changes in tumor size and weight of mice were measured twice a week." (PMID 35008490, 2021).
tumor (continued). "Cell from the circ-ZKSCAN1-overexpressed and NC groups were subcutaneously injected into BALB/c nude mice, and the tumor volumes were measured weekly." (PMID 31481066, 2019). "These TFs included tumor-promoting ZKSCAN1 from the open chromatin regions of metastases patients and tumor suppressor HNF1B from the open chromatin regions of non-metastases patients." (PMID 34439749, 2021). "Notably, several well-characterized cancer-related genes (e.g., ZKSCAN1, ABCB4 and CYP2C8) were found to generate circRNAs with significant changes in tumor samples." (PMID 31900416, 2020).
cancer (13 papers, 2017 to 2023). A tumor composed of atypical neoplastic, often pleomorphic cells that invade other tissues. "RNA-seq supported the hypothesis that ZKSCAN1 mRNA regulated cellular metabolism and circZKSCAN1 was involved in cancer-associated signaling pathway." (PMID 30191143, 2018). "Since, our gene expression profiling demonstrated a number of deregulated genes (e.g., PIKFYVE, ZKSCAN1, CYR61, ITGA3) associated with the microtubule cytoskeleton, we assumed that secalonic acid’s effect on microtubules may be related to its ability to inhibit cancer cell migration." (PMID 32679716, 2020). "In our study, we found that the expression of circZKSaa is significantly reduced in cancer tissues, while the expression of ZKSCAN1 did not change obviously." (PMID 36691031, 2023). "Thus, the two ZKSCAN1 gene post‐translational products (ZKSCAN1 mRNA and circRNA) play important roles in the development of human HCC cells, acting independently and cooperating closely with one another to promote cancer growth." (PMID 28211215, 2017).
ZKSCAN1 also shares sentences with these, for which no sentence is quoted: Cirrhosis (3 papers); lung carcinoma (2); osteosarcoma (2); adenocarcinoma (1); autism (1); bladder urothelial carcinoma (1); colorectal cancer (1); COVID-19 (1); glioma (1); Intellectual disability (1); liver cancer (1); lung adenocarcinoma (1); malignant glioma (1); melanoma (1); schizophrenia (1); spitzoid melanoma (1); stomach cancer (1); Wolf-Hirschhorn syndrome (1).